FGF2 (fibroblast growth factor 2)
Diseases named in the same sentence as FGF2 in open-access papers (continued):
Sharing a sentence is not in itself a finding about the gene and the disease.
infection (continued). "To determine whether Erk1/2 activation is necessary for up-regulation of fgf2 transcription in response to C. trachomatis infection, we monitored the effect of inhibiting Erk1/2 on fgf2 transcription during infection." (PMID 21998584, 2011). "Finally, we demonstrate that by enhancing secondary rounds of infection, C. trachomatis-induced up-regulation of FGF2 is physiologically important." (PMID 21998584, 2011). "Finally, we demonstrate the in vivo relevance of these findings by showing that conditioned medium from C. trachomatis infected cells is enriched for LMW FGF2, accounting for its ability to enhance C. trachomatis infectivity in additional rounds of infection." (PMID 21998584, 2011). "Released FGF2 is sufficient to enhance the subsequent rounds of infection." (PMID 21998584, 2011). "In addition, C. trachomatis stimulates FGF2 transcription, production, and release to facilitate additional rounds of infection." (PMID 21998584, 2011). "The Erk/MAPK kinase (MEK) inhibitor U0126 was added for the first 3 hrs of infection (0–3 hpi; to prevent the first wave of Erk1/2 activation) or for the last 4 hrs of infection (8–12 hpi; to prevent the second wave of Erk1/2 activation), and fgf2 transcription was assessed at 12 hpi." (PMID 21998584, 2011). "In addition to stimulating EB binding, we speculate that FGF2 production enhances secondary rounds of infection by its prosurvival activity." (PMID 21998584, 2011). "Finally, we demonstrate the in vivo relevance of these findings by showing that conditioned medium from C. trachomatis infected cells is enriched for FGF2 and that this accounts for its ability to enhance C. trachomatis infectivity in additional rounds of infection." (PMID 21998584, 2011). "These macrophages were notably elevated in patients hospitalized more than 10 days after infection onset, and their presence correlated with increased expression of angiogenic and hypoxia-related genes such as VEGFA, FGF2, and HIF1." (PMID 41472298, 2025). "Growth factors like FGF-2 and PDGF-BB are involved in tissue repair and fibrosis, crucial during recovery post-infection." (PMID 40557167, 2025). "Parasitic infection of colitic mice resulted in upregulation of mucosal AREG, EGF, FGF-2, and IGFBP-3 in the intestine of the host and better adaptation (infectivity)." (PMID 36836678, 2023). "Additionally, another study has shown that FGF2 gene transfer is able to restore hippocampal function in a transgenic model of AD mouse, whilst also enhancing Aβ phagocytosis and reducing Aβ production in primary cultured microglia and neurons after FGF2 infection." (PMID 36083518, 2022). "In HMECs, we observed a time-dependent increase in the expression levels of both FGF2 and FGFR1, with the maximum increase at 6 h post-infection (3.06 ± 0.2- and 3.01 ± 0.5-fold, respectively, p ≤ 0.01)." (PMID 30513762, 2018). "Unlike what was observed for inflammatory cytokine content, soluble proangiogenic factors assayed (FGF-2, HGF, and ANGPT-2) were constitutively expressed in the UI corneas and did not change as a result of VEH or AP20187 treatment following infection." (PMID 28903153, 2017). "Only FGF-1 was increased in early stage infection and other growth factors such as FGF-2 and IGF-1 were highly induced from 14 days after infection." (PMID 24351861, 2013). "Infections were performed in SFM, as the presence of exogenous FGF2 in serum would likely mask the effects of RNAi depletion." (PMID 21998584, 2011). "The expression of maturational factors did not increase during infection, though there were several differences in location, with FGF-2 located apically, and others such as VEGF and G-CSF in the basolateral compartment." (PMID 41157615, 2025). "Additionally, growth factors such as FGF2 and FGF20 were downregulated only in Delta infection and remained unaffected in Omicron." (PMID 41200555, 2025).
infection (continued). "Notably, direct infection of HMVEC-Ls induced the upregulation of VEGFA, ANGPT1 (angiopoietin-1), and FGF2 gene expression, as well as upregulation of VEGF receptor genes FLT1, KDR, and NRP1." (PMID 37773065, 2023). "This was associated with the decreased expression in mRNA of BDNF, NGF, and FGF2, and elevated expression of IL-1β in the hippocampus at 6 h post infection, but with no changes in optical intensity of the microglia and astrocytes." (PMID 35741412, 2022). "Cell supernatants were collected for 8 days and replenished with NPC media without FGF2 every 2 days after infection." (PMID 34769416, 2021). "Neither SMAD7 nor FGF2 expression levels were distinct following infection and did not appear to explain the differences in cytopathic effect seen in the current studies." (PMID 34372702, 2021). "HRV16 infection also led to a significant increase in expression of genes involved in EMT (e.g., COL1A1, MMP9, SNAI1, and ZEB2) and growth factors (e.g., ~ fourfold for EGF and FGF2, and to a lesser extent TGFB1)." (PMID 34140575, 2021). "Early release of FGF2-STAB® could promote cell proliferation at the beginning of healing, and gradual slow release of SeNPs could prevent infection in the subsequent stages of healing." (PMID 33849566, 2021). "While our data seems to suggest that pH1N1 infection results in a significant increase in FGF-2 expression regardless of the presence of MRSA, further investigation will need to be done to fully understand the role of FGF-2 in severe pH1N1-MRSA infections." (PMID 33202895, 2020). "A previous study showed that miR-194 expression was markedly decreased in A549 alveolar epithelial cells following infection with influenza A virus (IAV), and miR-194 could suppress fibroblast growth factor 2 (FGF2) expression at the mRNA and protein levels." (PMID 31438582, 2019). "In addition, we changed the virus titer for infection from MOI 10 to 30 and the fibroblast growth factor 2 (FGF2) concentration from 5 ng/ml to 30 ng/ml during the iPSC induction." (PMID 25479600, 2014). "Very few colonies appeared at day 20 post‐infection when the induction medium did not contain FGF2." (PMID 37190930, 2023). "Importantly, SR-0379 treatment resulted in rapid healing without infection compared to FGF2." (PMID 24675668, 2014). "In contrast, infection did not significantly impact cellular expression of EGF, FGF2, and VEGFB, and FGF1 expression was not reliably detected." (PMID 31569536, 2019). "We speculate the basal high contents of FGF-2 might explain the constitutive phosphorylation of ERK1/2 observed in the cornea, independent of infection or cell depletion." (PMID 28903153, 2017).
neurodegenerative disease (18 papers, 2006 to 2025). A disorder of the central nervous system characterized by gradual and progressive loss of neural tissue and neurologic function. "The neuroprotective effects of FGF2 have been demonstrated in many studies that FGF2 promotes proliferation of neural progenitor cells in neurogenic niches, enhances synaptic plasticity and axonal branching and ameliorates the behavioral deficiency in neurodegenerative diseases." (PMID 30135647, 2018). "Fgf2, critical for regeneration in lower vertebrates, has been implicated in compromising the RPE barrier function and precipitating degenerative diseases of the RPE in humans." (PMID 40722628, 2025). "Future work extending these studies to further investigate the effect of using HMW FGF-2 in vivo will determine if it can be used to treat neurodegenerative diseases such as AD." (PMID 32038161, 2019). "Targeting the FGF-2/FGFR3 pathway may give us clues for future therapeutic strategy against neurodegenerative diseases." (PMID 24735639, 2014). "Therefore, using FGF-2 or facilitating its release by microglia could be considered as potential therapeutic strategy for treating neurodegenerative diseases." (PMID 39683685, 2024). "Exogenous FGF2, either alone or in combination with other factors such as BDNF or endothelial GF (EGF), also promotes robust neuronal regeneration in neurodegenerative diseases, such as Huntington's disease." (PMID 34815808, 2021). "Fibroblast growth factor 2 (FGF2), a major ligand for FGFR1, shows a good therapeutic potential for the treatment of neurodegenerative diseases." (PMID 26939023, 2016).
cardiovascular disease (13 papers, 2018 to 2026). "Recent studies indicated that not only sαKlotho but also the entire sαKlotho/FGF-2 axis contributes to ongoing inflammation and the occurrence of fibrosis, leading to organ damage and cardiovascular disease." (PMID 39941530, 2025). "Fibroblast growth factor (FGF)-2 plays a crucial role in the pathophysiology of cardiovascular diseases (CVDs)." (PMID 29776409, 2018).
retinopathy (13 papers, 2012 to 2025). "Although the secretion dynamics of FGF2 in the retina remain unresolved, FGF2 expressing retinal microglia were found to drive pathological angiogenesis in retinopathy via either hypoxia-triggered necroptosis or lactylation in microglia." (PMID 40591415, 2025). "The results from this study provide evidence for changes in the expressions of BDNF, CNTF, and FGF-2 in Oxygen-induced retinopathy." (PMID 36532277, 2022). "Retinas of juvenile Sprague-Dawley rats have a remarkable intrinsic resistance to light-induced retinopathy, which correlated with overexpression of Fgf-2." (PMID 22291943, 2012). "FGF2 has been reported to be a contributor to pathologic fibrosis of the retina, and preclinical studies have explored its potential as a therapeutic target in rodent retinopathy models." (PMID 37191621, 2023). "Targeting the lactate/p300/YY1 lactylation/FGF2 axis may provide new therapeutic targets for proliferative retinopathies." (PMID 37085894, 2023). "This implies that targeting lactylase p300, YY1 lactylation, and FGF2 expression in macrophage may all provide new therapeutic targets for proliferative retinopathy." (PMID 37965331, 2023). "This study provides evidence for changes in BDNF, CNTF, and FGF-2 in Oxygen-induced retinopathy." (PMID 36532277, 2022). "Given their heterogeneity, therapeutic agents could be targeted solely to reactive retinal microglial cells, such as IL-34-dependent IPL-resident ones or FGF-2-releasing retinopathy-promoting ones." (PMID 35203414, 2022). "We recently performed gene expression analysis in a rodent T2DM model of retinopathy showing that growth factors like fibroblast growth factor 2 (FGF2) and placental growth factor (PGF) may be involved in the disease progression." (PMID 28575111, 2017). "Therefore, we sought to investigate whether APB5-induced retinopathy triggered the expression of FGF2 by microglia in the IPL, OPL, and SRS." (PMID 40591415, 2025). "The identification of FGF2, as dually expressed by microglia and vasculature in APB5 retinopathy, makes it a potential immunomodulatory target." (PMID 40591415, 2025). "Moreover, the interaction between EP300 and STAT3 is increased by treatment with CNTF or FGF2, suggesting a possible mechanism whereby CNTF and FGF2 reduce apoptosis and protect photoreceptor cells from light-induced retinopathy." (PMID 27242532, 2016).
kidney disease (11 papers, 2016 to 2025). "The accumulation of FGF-2 in the kidneys has been associated with the progression of several experimental and human kidney diseases." (PMID 34308967, 2021). "Taken together, all these findings suggest that changes in Rho-A and Rac-1 activity could play an important role in the pathogenesis of renal diseases associated with high circulating levels of FGF-2 and VEGF-A." (PMID 27097314, 2016). "In agreement with previous studies, FGF-2 was detected predominately in the peritubular interstitium of HIV-Tg26 mice with renal disease, where the FGF-2-binding sites were more significantly increased." (PMID 34308967, 2021). "Previous studies done in patients with HIV-renal diseases reported high plasma and urine levels of FGF-2 and VEGF-A." (PMID 27097314, 2016). "However, more [125I]-FGF-2 was accumulated in the kidneys of HIV-Tg26 mice with renal disease, compared to WT mice." (PMID 34308967, 2021). "In addition, we showed that the kidney of HIV-Tg26 mice with renal disease can act as a ‘sink’, trapping circulating FGF-2." (PMID 34308967, 2021). "To determine the systemic clearance and ability of the kidneys to recruit circulating FGF-2, we injected [125I]-FGF-2 intravenously into WT and HIV-T26 mice with renal disease." (PMID 34308967, 2021). "Urine samples from HIV-infected children with renal diseases showed high levels of VEGF-A and FGF-2, and induced similar changes in cultured REC and podocytes." (PMID 30418933, 2018). "Synergy between VEGF-A, FGF-2 and the HIV Tat protein affect the structure of renal endothelial cells and podocytes, leading to a precocious renal disease." (PMID 30418933, 2018). "Of all the FGF families, FGF2 (basic FGF (bFGF)) and its receptor, FGFR1, have been proven to be involved in the pathogenesis of renal disease by inducing fibrosis and contributing to renal damage in immune-mediated injury." (PMID 27331812, 2016). "Furthermore, urine samples from HIV+ children with renal diseases, showed high levels of VEGF-A and FGF-2, and induced similar changes in cultured REc and podocytes." (PMID 27097314, 2016). "Briefly, we demonstrated that FGF-2 was preferentially recruited in the kidneys of mice without pre-existing kidney disease, precipitating HIVAN by activating phosphorylated extracellular signal-regulated kinase (pERK) in renal epithelial cells, without inducing the expression of HIV-1 genes." (PMID 34308967, 2021). "Thus, a more complete knowledge of the pathogenesis of HIV-renal diseases cannot be obtained without understanding how FGF-2, VEGF-A, and HIV-Tat modulate the Rho family of GTPases in REc." (PMID 27097314, 2016). "However, previous studies showed that the accumulation of two heparin-binding growth factors, Vascular Endothelial Cell Growth Factor-A (VEGF-A) and Fibroblast Growth Factor-2 (FGF-2), in combination with the viral protein Tat, can precipitate the progression of HIV-renal diseases." (PMID 27097314, 2016). "Therefore we collected urine samples from HIV+ children with (HIV-RD) or without renal diseases (HIV-N), and measured the levels of FGF-2 and VEGF-A." (PMID 27097314, 2016).
vasculopathy (11 papers, 2013 to 2025). "Impaired tissue repair and angiogenesis, involving FGF1, FGF2, TGF-β, VEGF, and HIF-1α, has been implicated in vasculopathy and pseudoaneurysm formation in STAT3-HIES." (PMID 40491905, 2025).
neurological diseases (10 papers, 2013 to 2024). "Remarkably, about 13% of the DEGs in FGF2 treated S252W fibroblasts were associated with neurological diseases (BAT3, HS6ST1, IFI44L, RFC3, RPS9, STRC and TCF19)." (PMID 23593218, 2013). "The extensive landscape of neuroscience research has delved into the intricate relationship between Fgf2 and various neurological disorders, emphasizing its potential role in neural regeneration and repair processes." (PMID 38493090, 2024).
adenocarcinoma (8 papers, 2002 to 2021). A common cancer characterized by the presence of malignant glandular cells. "The results were comparable: VEGFA and VEGFR2 patterns of expression were similar; VEGFD, FGF2 were significantly downregulated as in lepidic adenocarcinomas and MMP2 was also significantly downregulated." (PMID 29137669, 2017). "Moreover, mRNA expression VEGFD, FGF2 MMP2, NRP1 and NRP2 was decreased in lepidic adenocarcinomas when compared to the normal lungs." (PMID 29137669, 2017). "On the contrary, we observed decreased mRNA expression of VEGFD, FGF2 and MMP2 and the absence of VEGFR2 proteins in human lepidic adenocarcinomas." (PMID 29137669, 2017).
heart disease (7 papers, 2014 to 2022). "One can extrapolate that during the development of hypertrophic and fibrotic heart disease hyper-secretory myofibroblastic cells would be likely to increase interstitial and pericardial Hi-FGF-2 content." (PMID 24827991, 2014). "The achievement of efficient cardiac differentiation using FGF2 may facilitate ES or iPS cell-derived cell therapy for heart diseases." (PMID 27803896, 2016). "Our work supports the notion that human Hi-FGF-2 in the heart is a clinically relevant target, and that strategies aimed at reducing endogenous Hi-FGF-2 production or activity should be considered to prevent maladaptive remodelling associated with heart disease." (PMID 24827991, 2014). "Signaling disorders of FGF2, FGF21, and FGF23 as paracrine signals also result in heart diseases." (PMID 27803896, 2016).
bacterial infection (5 papers, 2011 to 2024). "Further optimization of the fabrication parameters is needed to reduce the bacterial infection rate and improve the fixation strength at the bone-pin interface for the FGF-2-apatite composite layers prepared at 25 °C." (PMID 24918287, 2014). "Together, these results demonstrate that C. trachomatis utilizes multiple mechanisms to co-opt the host cell FGF2 pathway to enhance bacterial infection and spread." (PMID 21998584, 2011). "Together, these results demonstrate that C. trachomatis utilizes multiple mechanisms to co-opt the host cell FGF2 pathway that sets up a positive feedback loop to enhance bacterial infection and spread." (PMID 21998584, 2011). "Thus, C. trachomatis utilizes multiple mechanisms to co-opt the host cell FGF2 pathway to enhance bacterial infection and spread." (PMID 21998584, 2011).
inflammation (5 papers, 2014 to 2025). Aberrant reaction of the microcirculation characterized by movement of fluid and leukocytes from the blood into extravascular tissues. "More specifically, they found that FGF2 expressed by regulatory T cells cooperates with the cytokine IL-17 derived from Th17 cells to promote epithelial repair in a mouse model of intestinal inflammation." (PMID 36899862, 2023).
psychiatric disorder (5 papers, 2013 to 2025). A disorder characterized by behavioral and/or psychological abnormalities, often accompanied by physical symptoms. "Bdnf and Fgf2 are among multiple miRNA target genes linked to several psychiatric disorders including depression." (PMID 28751711, 2017). "Due to its importance in both brain development and function, it is not surprising that FGF2 has been implicated in a number of psychiatric disorders." (PMID 23675315, 2013). "Fibroblast growth factor 2 (FGF-2), which occurs in a high-molecular weight (HMW) and low-molecular weight (LMW) form, is a potent developmental modulator and nervous system regulator that has been suggested to play an important role in various psychiatric disorders." (PMID 30369869, 2018).
hematological cancers (4 papers, 2016 to 2025). "FGF-2 is associated with the progression and development of hematological cancers." (PMID 38473833, 2024). "The involvement of FGF2 in various stages of hematopoiesis suggests that its dysregulation can result in hematological cancers." (PMID 27007053, 2016). "FGF2 levels are frequently elevated in solids and hematological cancers." (PMID 29467390, 2018). "This review summarizes the biology of FGF signaling by demonstrating biological roles of FGF2 in regards to pathogenesis and prognosis of solid and hematological tumors with a special focus on clinical development of FGF2 inhibitors in the era of personalized medicine." (PMID 27007053, 2016).
hematological malignancies (4 papers, 2015 to 2021). "Compelling studies revealed that FGF2 could facilitate hematological malignancies through autocrine proliferative effects, and paracrine functions such as neovascularization." (PMID 27481339, 2016). "In conclusion, our data suggest that FGF2 may be a promising therapeutic target for hematological malignancies that propagate in the BM." (PMID 27481339, 2016).
bone disorder (2 papers, 2016 to 2021). "The first neutralizing mAbs to FGF2 were described in 1989–1991, but the role of FGF2 in bone diseases had long been unknown, and the discrepant reports were made on the role of FGF2 in bone disorders in 1998–2002." (PMID 27506449, 2016).